RNU6-1278P (RNA, U6 small nuclear 1278, pseudogene)
Gene: Small nuclear RNA gene on chromosome 18 (46,121,615 to 46,121,721, reverse strand). Ensembl gene ENSG00000251939.
Homologues: Orthologues: chimpanzee U6 (98% identical), macaque U6 (90% identical), dog U6 (79% identical), pig U6 (79% identical). Paralogues in human: RNU6-144P (84% identical), RNU6-333P (84% identical), RNU6-128P (82% identical), RNU6-16P (82% identical), RNU6-7 (82% identical), RNU6-8 (82% identical), RNU6-1 (81% identical), RNU6-15P (81% identical), RNU6-2 (81% identical), RNU6-20P (81% identical), RNU6-21P (81% identical), RNU6-25P (81% identical), and 1285 more.